CRABP2 (cellular retinoic acid binding protein 2)
Diseases named in the same sentence as CRABP2 in open-access papers (continued):
Sharing a sentence is not in itself a finding about the gene and the disease.
serous ovarian cancer (6 papers, 2020 to 2025). "Our IHC results confirmed that high expression of CRABP2 in tumor tissues was associated with a poorer prognosis, and multivariate survival analysis identified CRABP2 as an independent prognostic factor for serous ovarian cancer." (PMID 38195606, 2024). "Expression in serous ovarian cancer specimens was up-regulated, and CRABP2 expression was positively correlated with tumor grade and cancer stage." (PMID 38915108, 2024). "CRABP2 promotes epithelial mesenchymal transition (EMT) in serous ovarian cancer by upregulating the expression of enhancer of zeste homolog 2 and promoting the methylation of tripartite motif containing 16 (TRIM16)." (PMID 38807101, 2024). "The analysis showed that patients with high expression of CRABP2 had a poorer prognosis, and multivariate survival analysis showed that CRABP2 was an independent prognostic factor for serous ovarian cancer patients." (PMID 38195606, 2024). "Moreover, CRABP2 had been observed in serous ovarian cancer cells to enhance TRIM16 methylation through upregulation of EZH2, resulting in enhanced EMT effect." (PMID 38186580, 2023). "CRABP2 enhances the methylation of TRIM16 by elevating EZH2 expression, subsequently expediting the epithelial-mesenchymal transition in serous ovarian cancer cells." (PMID 39991584, 2025). "Further analysis revealed that CRABP2 mRNA was a risk factor for OS and PFS regardless of clinical stage or pathological grade, and specifically in serous ovarian cancer patients." (PMID 38195606, 2024).
gastric cancer (5 papers, 2022 to 2025). A primary or metastatic malignant neoplasm involving the stomach. "CRABP2 has been found to facilitate the advancement of gastric cancer, as well as mitigate mitochondrial apoptosis and foster resistance to oxaliplatin in gastric cancer via DNA hydroxymethylation." (PMID 39991584, 2025). "In terms of the mitochondrial pathway, gastric cancer cells use different mechanisms, such as cellular retinoic acid-binding protein 2 (CRABP2), Ajuba, and MUC20, to maintain mitochondrial homeostasis and resist apoptosis." (PMID 38370477, 2024). "Mechanisms underlying this resistance involve the overexpression of Cell Retinoic Acid Binding Protein 2 (CRABP2), which promotes the binding of BAX and PARKIN in gastric cancer cells, thereby facilitating ubiquitin-mediated BAX degradation and weakening of mitochondrial apoptosis." (PMID 38370477, 2024).
head and neck squamous cell carcinoma (5 papers, 2016 to 2025). A squamous cell carcinoma that arises from any of the following anatomic sites: lip and oral cavity, nasal cavity, paranasal sinuses, pharynx, larynx, and salivary glands. "On the contrary, in malignant peripheral nerve sheath tumors (MPNSTs), head and neck squamous cell carcinoma, and esophageal squamous cell carcinoma, CRABP2 exert a tumor-inhibiting effect." (PMID 34632074, 2021). "In head and neck squamous cell carcinoma, CRABP2 has been demonstrated to be highly methylated in the promoter region ranged from -450 to -117." (PMID 26839961, 2016).
neuroblastoma (5 papers, 2019 to 2025). Neuroblastoma (NB) is the most common solid, extracranial childhood tumor. "As it is known that CRABP1 sequesters RA in the cytoplasm, its elevated expression in neuroblastoma could cause RA resistance by limiting RA access to the nucleus mediated by its binding to CRABP2." (PMID 35490242, 2022). "Its elevated expression in neuroblastoma could cause RA resistance by limiting RA access to the nucleus, which is mediated by binding to CRABP2." (PMID 35490242, 2022). "Treatment of cells with this new PROTAC also induced efficient degradation of both c-IAP1 and CRABP-2 and blocked proliferation of neuroblastoma cells; however, the effects on either c-IAP2 or XIAP were not analysed." (PMID 31030225, 2019). "Using the PROTAC on neuroblastoma, degradation of CRABP-2 resulted in reduced cell migration." (PMID 31030225, 2019). "In this context, it is of relevance our finding that only the combined BGA002-RA treatment induced a concomitant downregulation of CRABP1 and upregulation of CRABP2 expression, reverting the CRABP1/2 balance in neuroblastoma cells." (PMID 35490242, 2022).
breast tumors (4 papers, 2014 to 2019). "Lentivirus vector-based shRNA technique was used to test the functional relevance of CRABP2 knockdown in breast tumors." (PMID 31419991, 2019). "In contrast to CRABP1, the great majority of breast tumor tissues scored positive for CRABP2, with 90.7 % and 95.4 % of the scored samples showing cytoplasmic and nuclear CRABP2 immunoreactivity, respectively." (PMID 26142905, 2015). "CRABP1 and CRABP2 expression in primary breast tumor tissues was analyzed using gene expression and tissue microarrays." (PMID 26142905, 2015). "Analysis of a qPCR array consisting of cDNA derived from samples of normal breast and various stages of human breast tumors (OriGene) showed that downregulation of KLF2 during disease progression is correlated with a marked decrease in the ratio of CRABP2 and FABP5 mRNAs." (PMID 26416422, 2015).
colorectal cancer (4 papers, 2021 to 2025). A primary or metastatic malignant neoplasm that affects the colon or rectum. "This cluster also exhibited elevated expression of CRABP2, which encodes an intracellular lipid-binding protein that influences colorectal cancer proliferation and metastasis through modulation of the MAPK signaling pathway." (PMID 41031085, 2025). "CRABP2 plays a dual role in colorectal cancer: it promotes proliferation and suppresses apoptosis through the nuclear CRABP2/RB1 axis and the cytoplasmic AFG3L2/SLC25A39 axis." (PMID 40305785, 2025). "In conclusion, RanGAP1 may exert an influence on the progression of colorectal cancer through its regulation of the MAPK signaling pathway via CRABP2." (PMID 38267624, 2024).
endometrial cancer (4 papers, 2020 to 2025). Primary or metastatic malignant neoplasm involving the endometrium (mucous membrane that lines the endometrial cavity). "Assessment of protein expression in endometrial cancer using the Human Protein Atlas demonstrated CRABP2 expression in 3 of 11 endometrial cancers." (PMID 32927694, 2020). "Given our recent description of the different roles of ER in breast and endometrial cancer, the interaction between CRABP2 and ER in endometrial cancer warrants further investigation." (PMID 32927694, 2020). "Our diet-induced obesity study was used to identify two novel biomarkers for endometrial cancer, A2M and CRABP2, both of which appear to have important prognostic implications." (PMID 32927694, 2020). "CRABP2 alterations were identified in 13% of endometrial cancers in the TCGA dataset." (PMID 32927694, 2020). "We also present novel data on the role of CRABP2 in endometrial cancer." (PMID 32927694, 2020). "Our finding that CRABP2 is an independent prognostic marker in endometrial cancer requires further validation; however, it is maybe an important novel biomarker in CN-high cancers, which have a poor prognosis." (PMID 32927694, 2020).
esophageal cancer (4 papers, 2016 to 2025). A primary or metastatic malignant neoplasm involving the esophagus. "The present study extracted TCGA and used the chip data in the library to explore the expression level of CRABP2 in esophageal cancer." (PMID 34632074, 2021). "The expression data of CRABP2 in esophageal cancer in TCGA and GEO were collected by the public database GEPIA." (PMID 34632074, 2021). "Compared with normal esophageal mucosal epithelium, there was lower CRABP2 gene mRNA in the esophageal cancer tissue, and the difference was statistically significant (p < 0.01)." (PMID 34632074, 2021). "In summary, by integrating public databases, it is found that CRABP2 is significantly low in EC and may participate in the development of esophageal cancer through related metabolism, which has a certain reference value for clinical treatment and judging the prognosis of esophageal cancer." (PMID 34632074, 2021). "The biological relationship between CRABP2 and FABP5 can be used as a target for the treatment of esophageal cancer remains to be further studied by this group." (PMID 34632074, 2021).
esophageal squamous cell carcinoma (4 papers, 2016 to 2025). Esophageal squamous cell carcinoma (ESCC) is a type of esophageal carcinoma (EC) that can affect any part of the esophagus, but is usually located in the upper or middle third. "CRABP2 as a suppressor factor is expected to be a potential prognosis marker for esophageal squamous cell carcinoma." (PMID 34632074, 2021). "Notably, patients with esophageal squamous cell carcinoma (ESCC) who exhibit higher CRABP2 expression have a significantly longer overall survival compared to those with lower CRABP2 expression." (PMID 39991584, 2025). "The purpose of this study was to explore the effect of CRABP2 and FABP5, and their ratio on prognosis in esophageal squamous cell carcinoma." (PMID 34632074, 2021). "Considering that both are closely related to retinoic acid, CRABP2 and FABP5 are expected to be targets for predicting esophageal squamous cell carcinoma and clinical treatment." (PMID 34632074, 2021).
metastatic disease (4 papers, 2018 to 2025). "Correlation analysis further revealed Cyto‐CRABP2 expression to be negatively correlated with the M‐stage (R = −0.438, p < 0.001), suggesting that higher cytoplasmic expression is associated with less advanced metastatic disease." (PMID 40305785, 2025). "In summary, the immunoexpression of RARA and CRABP2 was increased in samples from patients subjected to pre-surgical chemotherapy and in samples from patients with metastatic disease, respectively." (PMID 29378601, 2018).
Obesity (4 papers, 2016 to 2022). Accumulation of substantial excess body fat.
prostate carcinoma (4 papers, 2016 to 2025). A carcinoma that arises from epithelial cells of the prostate gland. "Previous studies have demonstrated that CRABP2 is epigenetically downregulated in a large number of carcinomas, such as prostate cancer, human head and neck tumors, astrocytic gliomas." (PMID 26839961, 2016). "For instance, in prostate cancer, CRABP2 enhances prostate cancer cell migration and invasion." (PMID 40657374, 2025). "However, the expression levels of CRABP2 based on gleason score group, nodal metastasis group, and molecular signature group in prostate cancer were lower than normal controls (all P < 0.05)." (PMID 33407865, 2021). "Interestingly, in line with its expression pattern in neck and head tumors and prostate cancer, CRABP2 was dramatically downregulated in the T tissues (n = 47, **p = 0.0001<0.01)." (PMID 26839961, 2016). "CRABP2 is the common DEG both in breast and prostate cancer." (PMID 33407865, 2021). "CRABP2, HPD, ZEB2 and CDK5R1 are the common DEGs both in breast and prostate cancer." (PMID 33407865, 2021).
thyroid cancer (4 papers, 2019 to 2025). "CRABP2 was found to be upregulated in thyroid carcinoma and promoted the invasion, migration in thyroid cancer cells." (PMID 38915108, 2024). "In thyroid cancer cells, the expression of CRABP2 was upregulated by LINC01816, thus promoting EMT of tumor." (PMID 38186580, 2023). "Additionally, CRABP2 promotes the progression of thyroid cancer through the Integrin/FAK/AKT Pathway, making it a potential therapeutic target in the treatment of thyroid cancer." (PMID 39991584, 2025).
embryonic carcinoma (3 papers, 2012 to 2021). "Crabp2 transcription is well-established as an RA target in primary cells and cell lines (e.g., human skin fibroblasts, F9 teratocarcinoma cells, P19 embryonic carcinoma cells, and ES cells)." (PMID 23118616, 2012).
glioma (3 papers, 2016 to 2022). A benign or malignant brain and spinal cord tumor that arises from glial cells (astrocytes, oligodendrocytes, ependymal cells). "One of the mechanisms of impaired differentiation of glioma cells is the reduced expression of CRABP2 (transcription factor related to retinoic acid signalling), which results from the general hypermethylation." (PMID 27145078, 2016). "Additionally, CRABP2 expression was reduced in high-grade gliomas and when comparing primary GBM tissues of short-term and long-term survivors Barbus and co-workers detected that RBP1 and CRABP2 expression was higher in GBMs of short-term survivors." (PMID 36010607, 2022).
hepatocellular carcinoma (3 papers, 2021 to 2026). A malignant tumor that arises from hepatocytes. "Downregulation of CRABP2 inhibits proliferation and metastasis and promotes cell apoptosis of hepatocellular carcinoma." (PMID 38915108, 2024). "In addition, hypermethylation of CRABP2 promoter had an unfavorable prognostic value for hepatocellular carcinoma patients." (PMID 38915108, 2024).
lymph node metastasis (3 papers, 2019 to 2023). "Analysis of clinical samples revealed that high CRABP2 levels were correlated with lymph node metastases, poor overall survival, and increased recurrence." (PMID 30696915, 2019). "Furthermore, recurrence was regarded as a dependent variable, and five factors such as differentiation of degree, AJCC stage, lymph node metastasis, hematogenous metastasis, and CRABP2 expression were regarded as arguments." (PMID 34632074, 2021). "Furthermore, the expressions of CRABP2 and AK4 were also significantly correlated with lymph node metastasis." (PMID 37004157, 2023).
medulloblastoma (3 papers, 2017 to 2023). A malignant, invasive embryonal neoplasm arising from the cerebellum. "For instance, CRABP2 is silenced in the RA-resistant medulloblastoma UW228-2 cells due to CpG island methylation in the promoter region." (PMID 31736873, 2019). "The human medulloblastoma UW228-2 cell line was cited as the control of CRABP2 methylation and gemcitabine as the demethylator control." (PMID 31736873, 2019). "We have found that DNA methylation is responsible for the low or silenced CRABP2 expression in medulloblastoma cells." (PMID 31736873, 2019). "Therefore, ATC THJ-11T and medulloblastoma UW228-2 cell lines were selected for this study because of their absence in CRABP2 expression and tolerance to RA treatment." (PMID 31736873, 2019). "Therefore, the status of CRABP2 expression is considered a critical element in determining RA sensitivity in cancer cells, including those of medulloblastoma and pancreatic cancers." (PMID 31736873, 2019). "DNMT inhibitor 5-aza-2′-deoxycytidinecytidine (5-aza) is thus able to restore CRABP2 expression and reverse RA resistance of UW228-2 medulloblastoma cells." (PMID 31736873, 2019). "Five CpG islands in the CRABP2 promoter region of ATC THJ-11T cells and medulloblastoma UW228-2 cells were methylated." (PMID 31736873, 2019). "Taken together, CpG island methylation in the CRABP2 promoter region is evidenced in RA-resistant human ATC THJ-11T and medulloblastoma UW228-2 cells, which can be largely erased by resveratrol in the same manner as gemcitabine, demonstrating the ability of resveratrol in DNA demethylation." (PMID 31736873, 2019).
melanoma (3 papers, 2011 to 2025). A malignant, usually aggressive tumor composed of atypical, neoplastic melanocytes. "The results of animal experiments had also demonstrated that CRABP2 overexpression promoted tumorigenesis of melanoma, and the underlying mechanism was worthy of further verification in mouse models." (PMID 38186580, 2023). "In melanoma, the expression level of CRABP2 in the high-TMB group was significantly higher than that in the low-TMB group, and was associated with poor prognosis." (PMID 38186580, 2023). "Compared to the control group, the mice models derived from melanoma cells with CRABP2 overexpression had significantly increased tumor weight and volume, while the body weight of mice did not have a significant difference." (PMID 38186580, 2023). "We attempted to explore the mechanism by which CRABP2 affects the efficacy of PD-1 inhibitors in melanoma at the single-cell level." (PMID 38186580, 2023). "It was found that for all patients and melanoma patients receiving PD-1 inhibitors included in the website, higher level of CRABP2 predicted adverse OS and PFS." (PMID 38186580, 2023). "The ROC curves showed that the values of area under the curve (AUC) predicted by CRABP2 for the sensitivity of PD-1 inhibitors in all tumor types and melanoma were 0.615 and 0.584." (PMID 38186580, 2023). "Following overexpression of cDNA plasmids of CRABP2 in A375 melanoma cells, melanoma cells were injected into BALB/C-nu/nu mice to create subcutaneous melanoma models." (PMID 38186580, 2023). "Umap and violin plot were used to explore the immune characteristics of CRABP2 gene in melanoma which responded well to PD-1 inhibitors." (PMID 38186580, 2023). "Therefore, to verify the relationship of CRABP2 and the prognosis of melanoma patients, we tested the tumorigenicity of melanoma cells with overexpression of CRABP2 in vivo." (PMID 38186580, 2023). "Through bioinformatics analysis, we found that the level of CRABP2 may be related to the response of melanoma to PD-1 and may become a new target to improve the efficacy of immunotherapy by influencing immune infiltration of CAFs." (PMID 38186580, 2023). "Furthermore, CRABP2 may function as a biomarker for predicting the effectiveness of PD-1 inhibitors in melanoma patients." (PMID 39991584, 2025).
pancreatic ductal adenocarcinoma (3 papers, 2017 to 2023). An infiltrating adenocarcinoma that arises from the epithelial cells of the pancreas. "Previous studies have observed a correlation between the expression of CAFs and CRABP2 in pancreatic ductal adenocarcinoma (PDAC), where the two transporters of ATRA, fatty acid binding protein 5 (FABP5) and CRABP2, always appear in a high FABP5: CRABP2 ratio in quiescent fibroblasts." (PMID 38186580, 2023).
psoriasis (3 papers, 2022 to 2025). An autoimmune condition characterized by red, well-delineated plaques with silvery scales that are usually on the extensor surfaces and scalp. "We found several regulators that have previously been reported to be increased in psoriasis, such as CRABP2 (a carrier protein for retinoic acid signaling pathways) and STAT3 (a central regulator of various immune responses)." (PMID 35874668, 2022). "We propose that the overexpression of CRABP2 and its downstream pathways are involved in the hyperkeratinization in psoriasis." (PMID 36536476, 2022). "Strategies such as modulating microbial community balance, targeting CRABP2‐mediated transcriptional regulation, or using Elafin levels to guide therapy decisions could open new avenues for personalized psoriasis management." (PMID 41028930, 2025). "Moreover, we found that CRABP2 was highly expressed in lesional skin samples taken from psoriasis patients, lowly expressed in lesional skin samples taken from atopic dermatitis (AD) patients and rarely expressed in healthy skin." (PMID 36536476, 2022).
squamous cell carcinoma (3 papers, 2015 to 2021). A carcinoma arising from squamous epithelial cells. "Furthermore, they found that the CRABP1, CRABP2, and FABP5 proteins were overexpressed in both benign papillomas and malignant squamous cell carcinomas (SCCs)." (PMID 26503156, 2015).